BCL2 (BCL2 apoptosis regulator)
Diseases named in the same sentence as BCL2 in open-access papers (continued):
Sharing a sentence is not in itself a finding about the gene and the disease.
lung carcinoma (continued). "BKA-073 not only overcomes radioresistance but also synergizes with Bcl-2 inhibitor venetoclax against lung cancer." (PMID 34373755, 2021). "The drug loaded nanotubes represented an effective system for inducing BCL‐2‐mediated apoptosis in lung cancer cells." (PMID 33173809, 2021). "In vitro analyses using lung cancer cells showed that Wogonin led to significantly increased levels of cleaved caspase-3 and Bad and significantly decreased Bcl-2 expression in a concentration-dependent manner." (PMID 34630106, 2021). "Clinical specimens from lung cancer patients demonstrate the up-regulation of B-cell lymphoma 2 (Bcl-2), an anti-apoptosis protein that plays a crucial role in drug resistance." (PMID 34383763, 2021). "As the previous study revealed that TDB modulates Bcl-2 family proteins in human lung cancer cells via mediating Akt signaling, the alteration of antiapoptosis Mcl-1 and Bcl-2 proteins was additionally examined in CSC-enriched spheroids treated with TDB." (PMID 34349823, 2021). "The upregulation of Bcl-2 has been reported to promote cell survival and chemotherapeutic resistance in lung cancer cells isolated from patients." (PMID 34349823, 2021). "In the hepatocarcinoma cell lines SMMC7721 and HepG2 as well as lung carcinoma A427 cells, lupeol was shown to induce low expression of the antiapoptotic protein Bcl-2 and upregulate the proapoptotic protein BAX." (PMID 32571387, 2020). "Upregulation of BCL-2 has been found to be involved in the mediation of chemotherapy resistance in human lung cancer and considered as a target for overcoming chemoresistance in lung cancer." (PMID 32668597, 2020). "Our results showed that after 10-HDA treatment of A549 human lung cancer cells, the expression level of antiapoptotic protein Bcl-2 decreased, and the expression of proapoptotic proteins BAX, cyto-c, caspase-3, and PARP increased in a time-dependent manner." (PMID 33376719, 2020). "Another experimental study showed that a combination of B-cell lymphoma 2 (Bcl-2) and mTOR inhibition led to increased radiosensitization in a lung cancer models." (PMID 32668776, 2020). "In particular, increased expressions of Bcl-2 and Mcl-1 reflect a poor prognosis for many malignancies, including lung cancer." (PMID 32260280, 2020). "This suggests that the survival of these lung cancer-cell lines is safeguarded by two or more pro-survival BCL-2 proteins with MCL-1 or BCL-XL being the dominant factor." (PMID 32913197, 2020). "Increasing evidence supports the crucial roles of CDC25A, BCL2, and c-Jun in promoting the proliferation, apoptosis, and radioresistance of lung cancer cells." (PMID 32943060, 2020). "Many studies have shown that the Bax/Bcl-2 ratio is the main factor for apoptosis induction in cancers such as breast, prostate, liver and lung cancer." (PMID 32873990, 2020). "The detailed in cellulo investigations perpetuate the role of TGP18 in the downregulation of BCL-2 transcription to induce apoptosis bestowing anti-tumor efficacy towards lung cancer cell line (A549)." (PMID 32929356, 2020). "In gastric cancer and lung cancer, the expression of miR-181a-5p through target BCL2 increased the sensitivity of cancer cells to cisplatin and vincristine, which further induced the apoptosis of cancer cells." (PMID 32724822, 2020).
lung carcinoma (continued). "Having shown the potential Mcl-1 suppression in H460 cells, we next confirmed the Mcl-1- and Bcl-2-targeting activity of TM-(–)-18 and TM-(–)-4a in primary lung cancer cells." (PMID 32260280, 2020). "We characterized all transcripts whose splicing relies on RNF113A and also established a link between RNF113A and MCL-1 stabilization, with important consequences for the treatment of lung cancer cells showing some acquired resistance to BCL-2 inhibitors." (PMID 32152280, 2020). "Our previous study showed that CSC can induce anti-apoptotic gene BCL-2 expression and promote lung cancer cell chemoresistance through downregulating Smad3 expression." (PMID 32668597, 2020). "It was noteworthy that while we showed in this study that RT reduced both Mcl-1 and Bcl-2 in primary lung cancer cells, RT was previously shown to have a minimal effect on Bcl-2 in H460 cells." (PMID 32260280, 2020). "It has been reported that, elevated expression of Bcl-2 has been observed in numerous types of cancer including lung cancer." (PMID 31817718, 2019). "We demonstrated that Cal14.1a induced apoptosis in lung cancer cell line H1299 via caspase activation and proapoptotic Bax/Bcl-2 ratio." (PMID 31861952, 2019). "Western blot and enzymatic activity experiments further confirmed that compound 15 further activated caspase-3 activity by up-regulating Bax and decreasing the level of Bcl-2 expression, thereby inducing apoptosis of lung cancer cells." (PMID 31640194, 2019). "Further, TIPE2 promoted lung cancer cell apoptosis via modulation of caspase-3, -9, Bcl-2, and Bax through the P38 and Akt pathways." (PMID 31817720, 2019). "si-Bcl-2 reduced the expression of antiapoptotic Bcl-2 and led to reduced cell viability in vitro of lung cancer cells when co-delivered with paclitaxel compared to paclitaxel-scrambled siRNA system." (PMID 30959799, 2019). "In this study, we characterize the MCL-1 inhibitor maritoclax alone or in combination with a BCL-2/xL inhibitor in a panel of lung cancer cell lines." (PMID 31150457, 2019). "BCL-2 actively associated with the most of tumor induction and an elevated levels of BCL-2 significantly reduced the survival of lung cancer patients." (PMID 31450709, 2019). "Considering the anti-apoptosis capability of BCL2 families, we assessed the apoptosis/pyroptosis of A549 lung cancer cells by detecting the expression of the cleaved Caspase-3 and Caspase-1, respectively." (PMID 31508368, 2019). "We conclude that ACEE induces apoptosis of lung cancer cells by modulating Bcl-2 and Bax protein levels." (PMID 30914735, 2019). "For example, small molecules ABT-737, Navitoclax and Venetoclax are potent BCL-2 inhibitors, which have shown promising efficacy against cancers including lung cancer." (PMID 31450709, 2019). "To evaluate the robustness of these observed effects, we performed similar experiments in melanoma, GIST, and lung cancer cell lines using AZD5991 or a BCL-2/BCL-XL inhibitor, AZD4320." (PMID 31727958, 2019). "Protein level analysis via Western blotting shows that in lung cancer cells treated with cisplatin or CRAd, the level of anti-apoptotic bcl-2 was reduced while pro-apoptotic bax and caspase-3 levels were enhanced." (PMID 30841620, 2019). "Our study demonstrates that anti-apoptotic Bcl-2 is upregulated in lung cancer cells that develop acquired resistance to standard of care chemotherapeutic paclitaxel." (PMID 29899843, 2018).
lung carcinoma (continued). "This peptide also induced apoptosis of multidrug resistant H69AR lung cancer cells that express Bcl-2 and inhibited their growth in 3D spheroids." (PMID 29899843, 2018). "Of interest, honokiol was also observed to induce apoptosis through increasing the expression of Bax, while decreasing the expression of Bcl-2 in KRAS-mutant lung cancer cells." (PMID 29892225, 2018). "We derived paclitaxel resistant cancer cells to ascertain if Bcl-2 expression is altered during the development of chemoresistance and to determine if Bcl-2 functional converting peptides can be used to selectively kill paclitaxel resistant lung cancer cells." (PMID 29899843, 2018). "In this study, anoikis sensitizing effect of avicequinone B in human lung cancer cells involved with the down-regulation of caveolin-1 together with the reduction of Mcl-1 and Bcl-2." (PMID 29631569, 2018). "The ruthenium methylimidazole complex caused cell cycle arrest at G0/G1 phase and induced apoptosis via the mitochondrial pathway, which involved ROS accumulation, mitochondrial dysfunction and Bcl-2 and caspase activation in lung cancer A549 cells." (PMID 29321581, 2018). "Compounds 1–3 stimulated both the expression of a pro-apoptotic protein, Bax, and the hyperphosphorylation of an anti-apoptotic regulator, Bcl-2, in human lung cancer cells." (PMID 30149516, 2018). "TRIM9 E3 ligase knockdown in human lung cancer tissues and cell lines reduces Bcl-2 expression while it activates the caspase-7 and caspase-9." (PMID 29479529, 2018). "Our results show that FZKA decoction promotes lung cancer cell apoptosis through STAT3/Bcl-2/caspase-3 signaling pathways." (PMID 30046347, 2018). "In conclusion, our results demonstrate Bcl-2 functional conversion through Nur77 peptide, NuBCP-9 is an exciting strategy to target paclitaxel and doxorubicin resistant lung cancer cells." (PMID 29899843, 2018). "Taken together, our data supports a new strategy for treating lung cancers that acquire resistance to chemotherapy through overexpression of Bcl-2." (PMID 29899843, 2018). "Overexpression of Bcl2 blocks TNF-related apoptosis-inducing ligand- (TRAIL-) induced apoptosis in human lung cancer cells." (PMID 29104726, 2017). "Further, given the observation by previous studies that NF-κB signaling regulates BCL-2 transcription, the RAP1–NF-κB–BCL2 axis is inferred in the lung cancer cells to induce CP resistance." (PMID 28518145, 2017). "It was also demonstrated that A-121047 can synergize with the BCL-2 inhibitor ABT-263 in killing lung cancer, esophageal cancer, and multiple myeloma cell lines." (PMID 27086916, 2017).
lung carcinoma (continued). "Nicotine activates downstream signaling of Bcl-2 inhibitors, interfering with the ubiquitination process and preventing Bcl-2 from being degraded in lung cancer cells, resulting in increased chemoresistance." (PMID 28959140, 2017). "Acutiaporberine induces apoptosis in human non-small-cell lung cancer PLA-801 cells and human lung cancer 95-D cells, accompanied by downregulation of the bcl-2 gene and upregulation of the bax gene." (PMID 29362667, 2017). "IL-11 facilitated lung cancer cell chemoresistance to cisplatin via the IL-11R/STAT3 signaling pathway by promoting activation of the anti-apoptotic proteins Bcl-2 and Survivin in lung adenocarcinoma." (PMID 29100303, 2017). "Knockdown of AKT expression suppressed lung cancer cell proliferation, and the molecules correlated with apoptosis such as Bcl-2 and caspase-3 are the downstream targets of Akt." (PMID 28061481, 2017). "We additionally addressed the apoptotic molecular component including PARP1, Bcl2 and Bax in lung cancer cells." (PMID 26754670, 2016). "The induction of MMP-2 and/or MMP-9 by Bcl-2 overexpression is mediated by AP-1 in lung cancer cells, furin and TGF-β in glioma cells, and the N-cadherin/FGF receptor/ERK pathway in squamous carcinoma cells." (PMID 26621844, 2016). "Cytotoxicity studies in four lung cancer cell lines were complemented with measurement of gene expression of apoptosis-related proteins Bcl-2, BAX and the pro-survival proteins NFκB-1 and COX-2, as well as quantification of caspase activity." (PMID 26861394, 2016). "NF-κB in lung cancer cells is responsible for the induction of several anti-apoptotic and pro-proliferative proteins, as well as inflammatory factors, including Bcl-XL, Bcl-2, PCNA, and IL-6." (PMID 27602766, 2016). "Translocation of STAT to the cell nucleus increases the levels of Bcl2/Bcl-xl proteins that are leading to decrease caspase-3 activity, tumor survival and radioresistant lung cancer cells." (PMID 27923354, 2016). "In lung cancer therapeutics, a pilot trial of combined use of anti-Bcl-2 G3139 antisense oligonucleotide and paclitaxel has been applied, but no objective responses were observed." (PMID 26675547, 2016). "Niclosamide as an effective STAT3 inhibitor has shown to block effectively STAT3/Bcl2/Bcl-xl and to reduce the radioresistance in animal lung cancer xenografts." (PMID 27923354, 2016). "This study demonstrates that s-cal14.1a induces cell death of lung cancer cell lines, gene expression levels of proteins involved in regulating and executing apoptosis reveal an interesting pattern for Bcl-2 and BAX mRNA levels." (PMID 26861394, 2016). "Because abnormally high levels of BCL2 sustain these tumors, there has been much interest in targeting BCL2 as a novel approach to treat lung cancer." (PMID 26325180, 2015). "Studies also showed that increases of the expression of Bcl-2 have correlated well with the development of human malignancies, for example, in lung cancer." (PMID 26041886, 2015). "Upon nicotine treatment, it was demonstrated that via activating the mitogenic signaling pathways, Bcl-2 ubiquitination and degradation processes were attenuated, which facilitated the establishment of the chemo-resistance in lung cancer cells." (PMID 26041886, 2015). "We analyzed the expression of the anti-apoptotic proteins Bcl-2, Bcl-xL, and Mcl-1 in different lung cancer cells, and high GCS-expressing cancer cells also showed markedly increased Bcl-xL expression." (PMID 26001295, 2015). "Collectively, we discovered miR-206 targets 3′-UTR of c-Met and Bcl2 mRNA, and inhibits the expression of c-Met and Bcl2 in lung cancer cell lines (A549 and SK-MES-1)." (PMID 26325180, 2015). "In our present study, we initially demonstrated that miR-206 promoted lung cancer cell (A549) death, by targeting 3′-UTR of BCL2, which encoded pro-survive protein Bcl2, and increased the casepase-3 activities." (PMID 26325180, 2015).
lung carcinoma (continued). "We demonstrated that Bcl-2 in Swiss3T3 cells ectopically expressing or murine lung cancer LKR cells harboring K-ras rapidly underwent ubiquitin-dependent proteasome pathway after the treatment of GO6976, accompanied with induction of apoptosis." (PMID 26041886, 2015). "Taken together, these findings suggest that combinatorial TP/HCPT drug regimens induce caspase-dependent apoptosis in A549 lung cancer cells mainly through modulating the Bax- and Bcl-2-triggered mitochondrial pathway." (PMID 25573072, 2015). "Conversely, up-regulation of c-Met and Bcl2 were confirmed in tissue samples of human lung cancer, with its level inversely correlated with miR-206 expression." (PMID 26325180, 2015). "miR-34a-5p mimics, for example, simultaneously suppressed CDK4, MET and B-cell CLL/lymphoma 2 (BCL-2) in lung cancer xenografts by intravenous injection." (PMID 26439688, 2015). "This paradox of an anti-apoptotic protein can be explained by the upregulation of Bim in lung cancer upon Bcl-2 overexpression that makes Bim easily available upon exposure to stress stimuli." (PMID 26405162, 2015). "Silence of MET and BCL2 expression inhibits lung cancer cell (A549 and SK-MES-1) growth, migration, invasion and apoptosis." (PMID 26325180, 2015). "Glutathione peroxidase inhibits cisplatin-induced apoptosis via the down-regulation of Bcl2 in NCI-H460 human lung cancer cells." (PMID 24618722, 2014). "In support of this, we found that high levels of endogenous Bcl2 are expressed in several lung cancer cell lines, including those from SCLC and NSCLC." (PMID 24967145, 2014). "Our previous results confirmed that suppression of Akt and the NF-κB/Bcl-2 pathway by anticancer agents inhibited the migration and growth as well as induced the apoptosis in human breast and lung cancer cells." (PMID 25138052, 2014). "It has been reported that Bcl-2 proteins are overexpressed in many different solid tumors such as breast, prostate, and lung cancer and that serum Bcl-2 levels are also significantly higher in patients with ovarian cancer." (PMID 25180175, 2014). "It was found that miR-200bc/429 cluster was able to modulate multidrug resistance (MDR) in lung cancer cell lines, at least in part by inhibiting the antiapoptotic Bcl-2 and XIAP protein expression, thus affecting the mitochondrial release of cytochrome c." (PMID 24999473, 2014). "ERK1 and ERK2 have been identified as physiological Bcl2 kinases, suggesting that nicotine should have the capacity to regulate Bcl2 to support survival and potentially promote lung cancer development." (PMID 24967145, 2014). "High levels of Bcl2 are expressed in human lung cancer cells, while the level appears to be low in normal lung cells." (PMID 24967145, 2014). "CuB also induced lung cancer cell apoptosis through cytochrome c release, Bcl-2 downregulation and STAT3 pathway inhibition." (PMID 25242136, 2014). "Together these results demonstrate miR-181b's ability to modulate the development of MDR in lung cancer cell lines, at least in part, by modulation of apoptosis through the targeting of the antiapoptotic BCL-2." (PMID 24999473, 2014). "Although treatment with CFZ or CPPD did not significantly modulate Bcl-2 levels in the H1993 or SHP77 cells, future studies should investigate the combined activity of CFZ with Bcl-2 and/or Mcl-1 inhibitors in lung cancer." (PMID 25612802, 2014). "The overexpression of Bcl-2, an anti-apoptosis member of this family, is commonly observed in human lung cancer and Bcl-2 overexpression correlates with chemoresistance in this disease." (PMID 24137360, 2013). "It has been recently reported that inhibition of EGFR by erlotinib activates the STAT3/Bcl2/Bcl-XL survival signaling pathway in human lung cancer." (PMID 24019973, 2013). "Our previous study also found this phenomenon in human lung cancer cells (A549 cells) in which klotho also conferred a pro-apoptotic effect through the bax/bcl-2 pathway." (PMID 23437382, 2013).